TRAF6 (TNF receptor associated factor 6)
Diseases named in the same sentence as TRAF6 in open-access papers (continued):
Sharing a sentence is not in itself a finding about the gene and the disease.
infection (continued). "MRNA levels of genes encoding for chemokines (CXCL1 and CXCL5), cytokines (IL-10, IL-15 and IL-32), pattern recognition receptors (TLR1) and innate signaling molecules like IRAK3 and TRAF6, were all increased after MVA-C infection in comparison with MVA-WT-infected cells." (PMID 22536391, 2012). "This is in consistence with our mRNA microarray data showing decreased TRAF6 levels in progressing infection (data not shown)." (PMID 21629653, 2011). "The absence of TRAF6 resulted in enhanced viral replication and a significant reduction in the production of IL-6 and type I IFNs after infection with RNA virus." (PMID 19479062, 2009). "It has recently been reported that production of type I IFNs derived from DCs and MEF cells in response to infection with vesicular stomatitis virus (VSV) is significantly lower in the absence of TRAF6." (PMID 19479062, 2009). "In contrast to what we show here, two groups previously reported that TRAF6 is not involved in RLH-mediated antiviral responses by showing that Traf6−/− MEF cells produce normal levels of type I IFNs in response to infection with wild-type SeV." (PMID 19479062, 2009). "Nevertheless, with NF-kB 1 inhibition, MyD88 was significantly (p = 0.0047) up-regulated 1.28 - fold at 1 h post-infection, whereas no significant change was found in TRAF6 expression." (PMID 21637513, 2009). "RNF19A was shown to be recruited to TRAF6 by the NOD family member NLRP11, which is rapidly induced by LPS in macrophages and then rapidly degraded itself, suggesting that it might act specifically during the resolution phase of infection." (PMID 33808506, 2021). "In susceptible patients (State 1) at the time of infection, the host may not be able to recognize these bacteria through the respective TLRs because the downstream IRAK/TRAF6 module has been overwhelmed by intrinsic signals." (PMID 19390631, 2009). "However, TRAF6 is dispensable for IRF3 activation because the dimerization of IRF3, an indicator of IRF3 activation, occurred normally in Traf6−/− MEF cells following either transfection with poly I:C or infection with NDV or SeV Cm." (PMID 19479062, 2009). "In addition, TRAF6, P65 and IKKβ are significantly activated at the early stage of NIBV infection, and NIBV can significantly increase the protein levels of IPS-1, TRAF6, P65 and P50, and most of the proteins are most significantly expressed at 36 hpi after infection with the virus." (PMID 41327426, 2025). "However, with the inhibition of siNF-kB 1, a dramatic up-regulation of MyD88 at 1 h post-infection was observed, while no significant change was found for TRAF6, except for an even lower expression at 4 h post-infection for some unknown reason." (PMID 21637513, 2009). "We also observed that the mRNA transcript levels of MyD88 and other proteins in the MyD88 signaling pathway (TIRAP, TRAM, TRIF, and TRAF6, not shown) are similar after low MOI infection with WT TB40/E or UL88-STOP virus." (PMID 40638072, 2025). "The expression pattern of anti-inflammatory miRNAs 146a and 124, and the inflammatory mediator TRAF6 and IRAK1, suggest an acute increase in inflammation in the early stages of infection, followed by negative feedback." (PMID 37376550, 2023). "In human nasal epithelial cells (hNECs), after infection with influenza H3N2 virus, miR-146a was induced, regulating TRAF6 expression but not IRAK expression in the nasal epithelium; in contrast, it targeted IRAK1 in the lower airway." (PMID 36142450, 2022). "The lack of TRAF6 leads to enhanced viral replication and a significant reduction in the production of type I IFN after infection with RNA virus." (PMID 31636617, 2019). "Altogether, these results show that HBP is a key bacterial PAMP sensed by epithelial cells during infection by both invasive and extracellular gram-negative bacteria and that TIFA/TRAF6-dependent innate immunity against HBP is controlled by ALPK1." (PMID 28222186, 2017).
infection (continued). "Depletion of neither TIFA nor TRAF6 had an impact on L. monocytogenes-induced IL-8 production and TIFA failed to form oligomers after infection." (PMID 28222186, 2017). "As would be expected, TRAF6 and IRAK1 were decreased in LV-Omp25-infected cells compared to the cells infected with LV-Blank 24 h post-infection, with no change for IRAK2." (PMID 29387067, 2017). "The expression levels of Unigene 34569 (Cu/Zn SOD), Unigene 16729 (TRAF6) and nLvALF2 in hr group and lr group showed significant differences (P < 0.01) in shrimp without WSSV infection." (PMID 28094323, 2017). "To further decipher the role of TRAF6 in the IFN antiviral response, we evaluated HIV-1 replication, 24 hours after infection of IFNα2 pre-treated or not macrophages." (PMID 22140520, 2011). "Quantification of viral replication by the plaque assay showed that viral yields were significantly higher in Traf6−/− MEF cells than in Traf6+/+ MEF cells at 48 and 72 h after infection with Newcastle disease virus (NDV), a negative-sense ssRNA recognized by RIG-I." (PMID 19479062, 2009). "Infection with NDV did not induce NF-κB activation in Traf6−/− MEF cells that ectopically expressed T6Rm, suggesting that the E3 ubiquitin ligase activity of TRAF6 is required for NF-κB activation, as is the case in TLR signaling." (PMID 19479062, 2009). "In line with a previous report, our findings suggest that PEDV may exploit kinase-dependent pathways, such as MAPK/AP-1 and JNK/p38, via TRAF2, TRAF6, and TBK1 to enhance viral replication during the acute phase of infection in weaned piglets, whereas such modulation was absent in newborn piglets." (PMID 40589734, 2025). "However, dietary BLJ supplementation remarkably downregulated TLR-4 and TRAF-6 gene expression levels, decreased IL-1β gene expression levels and increased A20 and SOCS-6 mRNA levels in the jejunal mucosa of broilers regardless of NE infection." (PMID 32110391, 2020).
bacterial infection (25 papers, 2013 to 2024). "The TRAF6-Ecsit complex is required for mitochondrial recruitment to phagosomes, hence, disruption of the TRAF6-Ecsit complex would severely dampen ROS production and therefore increase susceptibility to bacterial infection." (PMID 34379706, 2021). "Our current study suggests that increased K63-linked polyubiquitination and activation of TRAF6 E3 ligase is one of the underlying mechanisms leading to the enhanced inflammatory responses seen in post viral–bacterial infections." (PMID 29515583, 2018). "For example, miR-146a can modulate the innate immune response to bacterial infection by targeting the TNF receptor associated factor 6 (TRAF6) and interleukin receptor associated enzyme I (IRAK1)." (PMID 25749476, 2015). "miR-146a, for example, regulates the innate immune response to bacterial infection, targeting TNF receptor-associated factor 6 (TRAF6) and Interleukin-1 receptor-associated kinase 1 (IRAK1), while miR-150 regulates the production of mature B cells." (PMID 23472090, 2013). "In the gut, YTHDF1 recognizes the target TNF receptor associated factor 6 (TRAF6) transcript to modulate the gut immune response to bacterial infection, by the unique interaction mechanism between the P/Q/N-rich domain and host factor DEAD (Asp-Glu-Ala-Asp) box polypeptide 60 (DDX60) death domain." (PMID 36835655, 2023). "YTHDF1 is essential for IECs’ defense against bacterial infection by regulating Traf6 expression, a pivotal regulator of TLRs and NF-κB signaling." (PMID 38830900, 2024). "Both TRAF6 and Ecsit have also been reported to regulate the expression of AMPs during bacterial infection in marine crustaceans." (PMID 34379706, 2021). "TLR1/2/4 sensed bacterial infections and triggered assembly of the TRAF6-ECSIT (evolutionarily conserved signaling intermediate in Toll pathways) complex, which was required for juxtaposition of mitochondria and phagosomes." (PMID 32174922, 2020). "Recently, alpha-kinase 1 (ALPK1) controlling TIFA/TRAF6-dependent innate immunity against bacterial infection is gradually reported." (PMID 32420802, 2020). "Based on microarray analysis and Taqman miRNA assays we conclude that members of the miR-146 family, which is highly conserved between fish and human, are induced by bacterial infection in zebrafish in a MyD88 and Traf6 dependent manner." (PMID 24112639, 2013). "In the present study, it was observed that TRAF6 cooperates with Ecsit to regulate mROS and the expression of ALFs in mitochondria and nuclei, respectively, which further affects hemolymph microbiota homeostasis in response to bacterial infection in mud crabs." (PMID 34379706, 2021). "Specifically, YTHDF1 facilitates the transcription and expression of m6A-modified Traf6 mRNA in a DDX60-dependent manner, ultimately impairing IECs’ defense against bacterial infection." (PMID 38830900, 2024). "STK3/4 also activates Rac GTPase, promoting the assembly of the TRAF6-ECSIT complex, which is crucial for immune T cells to resist bacterial infections." (PMID 38436783, 2024). "The chemokine ccl20b plays an important role in viral and bacterial infections in fish and is upregulated via STAT6 which is stabilized by binding to TRAF6, reducing its ubiquitination." (PMID 37808550, 2023). "In this study, we demonstrated that SLAMF7 was inducibly expressed on macrophages in response to TLR ligands and bacterial infection and that it interacted with SHIP1 and TRAF6 to attenuate MAPK and NF-κB signaling–mediated proinflammatory cytokine production." (PMID 36749634, 2023). "Upon bacterial infection, the germinal center kinase MST4 can directly phosphorylate the adaptor TRAF6 to limit the inflammatory responses, thereby avoiding the damage caused by excessive immune activation." (PMID 35820905, 2022). "In the intestinal immune response to bacterial infection, YTHDF1 can facilitate the immune inflammatory response by regulating the transcription of TRAF6." (PMID 36550542, 2022).
bacterial infection (continued). "Similar study supported a model in which m6A modifications in the Traf6 transcript regulated the intestinal immune response to bacterial infection via a complex consisting of YTHDF1, DDX60, and the Traf6 transcript." (PMID 36578521, 2022). "Upon bacterial infection of IECs, ALPK1 has been shown to signal through TRIF/TRAF6 to NF-κB, triggering secretion of proinflammatory cytokines like IL8 and TNFα." (PMID 32076438, 2020). "Future studies will need to determine if S1PR2 can co-localize with TLR4, MyD88, RANK, TRAF6, MAPKs, PI3K, Src, and integrins in lipid rafts in response to bacterial infection or RANKL stimulation." (PMID 30609675, 2019). "Besides its expression dynamically responding to bacterial infection, MST4 can also directly phosphorylate the adaptor TRAF6 to limit the inflammatory responses, thereby avoiding the damage caused by excessive immune activation." (PMID 35820905, 2022). "Indeed, it has been reported that TRAF6 mediates K63 ubiquitination via the SH2 domain of STAT3, which is an essential step for STAT3 phosphorylation in response to bacterial infections." (PMID 33717204, 2021). "After recognizing bacterial infection, TLRs activated MST1/2, which phosphorylated PKC-α and activated PKC-α-LyGDI (Rho-specific guanine nucleotide dissociation inhibitor)-Rac axis, promoting assembly of the TRAF6-ECSIT complex and ROS production." (PMID 32174922, 2020). "In addition, it was found that the expression of MyD88, TRAF6 and TAK1 molecules are involved in the mechanism of TLR4 in human endometrial endothelial cell responses to bacterial infection." (PMID 25371751, 2014).
inflammation (10 papers, 2012 to 2024). Aberrant reaction of the microcirculation characterized by movement of fluid and leukocytes from the blood into extravascular tissues. "Thus, complete loss of TRAF6 or selective inactivation of MALT1 catalytic function in mice skews the immune system towards autoimmune inflammation, but distinct mechanisms are responsible for these immune disorders." (PMID 36761777, 2023). "Both regulations of miR-146a expression and silencing of TNF receptor-associated factor-6 (TRAF-6) resulted in a significant reduction in stress-induced cytokine secretion, suggesting that miR-146a targets the potential role of TRAF-6 in airway inflammation." (PMID 35241728, 2022). "Our results therefore suggest that the PEP-sNASP may provide a potential protein therapy against oxidative stress and pulmonary inflammation via selective TRAF6 signaling." (PMID 35386914, 2022). "Thus, downregulation of TRAF6 signalling seems to be the most likely mechanism of HIF-1-mediated attenuation of periapical inflammation." (PMID 29654284, 2018). "It is, therefore, hypothesized that synovial TRAF6 is involved in the pathogenesis of synovial inflammation and osteoclast differentiation in RA." (PMID 22656185, 2012). "Thus, we postulated that elevated synovial TRAF6 expression may be involved in the pathogenesis of RA synovial inflammation." (PMID 22656185, 2012). "The western blot results showed that TLR4/MyD88/Traf6 was elevated after METH treatment, suggesting that METH treatment induced liver inflammation, and antibiotics pretreatment can reverse this elevation." (PMID 34381368, 2021).
neurodegenerative disease (9 papers, 2013 to 2025). A disorder of the central nervous system characterized by gradual and progressive loss of neural tissue and neurologic function. "Instead of conventional K63-linked polyubiquitination, TRAF6 promotes atypical ubiquitination of DJ-1, aSYN and N-HTT with K6, K27, and K29 linkage formation, thereby stimulating aggregate formation of mutant DJ-1, aSYN and N-HTT in neurodegenerative diseases." (PMID 23758787, 2013).
cardiovascular diseases (6 papers, 2012 to 2024). "TRAF6 signaling is implicated in inflammation and cardiovascular disease." (PMID 36305766, 2022). "The influence of CD137 signaling on the expression of NFATc1 through TRAF6 and NF-κB p65 may have extensive implications for the diagnosis and therapeutic intervention for a variety of proliferative cardiovascular diseases." (PMID 26600673, 2015).
immune disorders (6 papers, 2009 to 2023). "TNF receptor-associated factor 6 (TRAF6), a signal transducer for inflammatory signaling, plays crucial roles in the pathogenesis of immune diseases." (PMID 35668944, 2022). "Since recent report revealed that TRAF6 is associated with RA and SLE patients, TRAF6 and its signaling molecules could be responsible for Treg dysfunction in human immune disorders." (PMID 24058613, 2013). "Therefore, a further understanding of the molecular mechanism associated with TRAF6-mediated signal transduction is required in order to enable the development of therapies against various immune diseases." (PMID 19479062, 2009). "B. breve CCFM1026 significantly reduced the proportion of neutrophils and increased lymphocytes, the expressions of TLR7, MyD88, TRAF6, and TNF-α to restore the immune disorders." (PMID 33924002, 2021).
metabolic disease (4 papers, 2019 to 2025). A congenital disorder (due to inherited enzyme abnormality) or acquired (due to failure of a metabolically important organ) disorder resulting from an abnormal metabolic process. "By using several animal models of metabolic diseases, we identify macrophage MVP as an important suppressor of NF-κB activation by preventing TRAF6 ubiquitination." (PMID 30996248, 2019). "Conceivably, the autonomous negative regulation of TRAF6 by different factors including MVP may determine the precise role of IKK and as such the outcomes in the metabolic diseases." (PMID 30996248, 2019).
neurological diseases (4 papers, 2020 to 2026). "Our findings demonstrate that BMSC-derived exosomal via miR-146a-5p modulates microglial polarization by targeting Traf6, providing a potential thermal target for the treatment of neurological diseases involving microglial activation." (PMID 38025715, 2023). "In addition, miR-146a participates in the neuroinflammatory response of different neurological diseases by regulating the common inflammation-related target genes (IRAK1, TRAF6, and CFH) and related pathways (TLR signaling pathway and complement activation pathway)." (PMID 32581706, 2020).
infectious disease (2 papers, 2022 to 2023). A disorder directly resulting from the presence and activity of a microbial, viral, or parasitic agent in humans. "Recent reports have suggested that TRAF6 has several different functions in infectious diseases." (PMID 38016969, 2023).
digestive tumours (1 paper, 2024). "Our analysis of PPI networks identified 11 hub genes (Myd88, Traf6, Irf7, Cdk4, Ccnd2, Mapkap1, Prr5, Mpp3, Serpinb6b and Pvrl3) that were implicated in digestive tumours." (PMID 38434966, 2024). "The PPI networks identified 10 hub genes that were implicated in digestive tumour immunotherapy target TIM-3 (Myd88, Traf6, Irf7, Cdk4, Ccnd2, Mapkap1, Prr5, Mpp3, Serpinb6b and Pvrl3)." (PMID 38434966, 2024).
hematologic malignancies (1 paper, 2022). "In addition to its role in inflammatory pathways, deregulated TRAF6 expression appears to be a key feature in hematologic malignancies." (PMID 36172375, 2022).
TRAF6 also shares sentences with these, for which no sentence is quoted: cardiomyopathy (4 papers); skin cancer (4); Hypertension (3); non-alcoholic steatohepatitis (3); postmenopausal osteoporosis (3); Atrophy (2); bladder cancer (2); central nervous system diseases (2); cholangiocarcinoma (2); Hepatitis (2); measles (2); nasopharyngeal carcinoma (2); neutropenia (2); obstructive jaundice (2); oral squamous cell carcinoma (2); peritonitis (2); Respiratory Diseases (2); subarachnoid hemorrhage (2); tendinopathies (2); uveitis (2); acne (1); acute coronary syndrome (1); acute kidney injury (1); acute leukemia (1); acute myocardial infarction (1); acute-on-chronic liver failure (1); adult-onset Still disease (1); allergic asthma (1); amyotrophic lateral sclerosis (1); anhidrosis (1).
A further 78 diseases each share a sentence with TRAF6 in 1 paper.